CRP (C-reactive protein)
Diseases named in the same sentence as CRP in open-access papers (continued):
Sharing a sentence is not in itself a finding about the gene and the disease.
viral infections (continued). "CD64 has previously been reported to, more reliably than CRP, differentiate systemic infections from rheumatic disease, surgical trauma and viral infection." (PMID 23783182, 2013). "Better quality studies are needed to address the utility of CRP testing for pediatric infections and to define a consistent optimal cutoff value that can discriminate bacterial from viral infections or other diseases." (PMID 22943554, 2012). "SAA and CRP levels were also found to be higher in bacterial infections than in viral infections, although SAA appeared to be more clinically relevant as a marker of inflammation in acute viral infections." (PMID 22427910, 2012). "CRP levels are commonly associated with infection; however, they are not elevated in all cases, particularly viral infections when compared to bacterial infections." (PMID 40123598, 2025). "During the viral infection course, increased synthesis of proinflammatory markers such as C-reactive protein (CRP), tumor necrosis factor-alpha (TNF-α), ferritin and interleukins increase consumption of albumin and muscle protein, which is the main cause of susceptibility to malnutrition." (PMID 40429378, 2025). "In our study, conducted on a population of 615 infants aged between 0 and 90 days, we analysed the diagnostic power of CRP, PCT, WBC and ANC in differentiating between viral infections, UTI and SBI, both individually and in combination with other clinical and laboratory data." (PMID 41065831, 2025). "In addition, ddhC outperformed in differentiating viral infections from all other groups compared to CRP, white cell count, and lymphocyte count." (PMID 39861921, 2025). "However, both MxA alone and the MxA/CRP ratio showed poor performance in differentiating viral infections from mixed infections, with AUCs of 0.5161 and 0.5429, respectively." (PMID 40046054, 2025). "Furthermore, the most significant increases in mean CRP levels have been observed in patients aged >65 years, and in bacterial-viral infections, CRP levels can exceed 200 mg/L." (PMID 41210881, 2025). "Notably, SAA exhibits superior sensitivity for low-grade inflammation, detecting early viral infections even when CRP remains normal." (PMID 41308272, 2025). "While IL-6 showed weak correlation with CRP during Days 1–2 of fever (r = 0.25, p = 0.02), serum amyloid A demonstrated superior sensitivity for bacteremia (100% vs. CRP’s 68%)—though the study cautioned against its standalone use due to false-positives in viral infections." (PMID 40647525, 2025). "In approximately half of the patients, GPs performed CRP-POCTs to decide whether antibiotic treatment was necessary (55.0%) and to differentiate between bacterial and viral infections (48.0%)." (PMID 39159989, 2025). "The use of blood tests, especially white blood count, neutrophil count, and biomarkers such as C-reactive protein and procalcitonin, has been explored as a means to differentiate between bacterial and viral infections, particularly in cases where clinical presentation is inconclusive." (PMID 40142420, 2025). "The primary purpose of CRP testing was to differentiate between bacterial and viral infections." (PMID 39313318, 2025). "However, both fever and CRP have limited reliability in distinguishing bacterial from viral infection." (PMID 41153485, 2025). "Additionally, CRP is a generic measure of inflammation, and HSV-1 and CMV are related to viral infection making it hard to pinpoint causality." (PMID 40815085, 2025). "Similarly, CRP, an acute-phase protein synthesized in the liver, is known to increase significantly during bacterial infections but remains relatively low in viral infections." (PMID 40595978, 2025). "As CRP levels in malaria-infected individuals can be similar to those seen in the context of bacterial infection, the presence of parasitemia should be taken into consideration when applying CRP to differentiate bacterial from viral infections." (PMID 38241274, 2024).
viral infections (continued). "However, its discriminatory ability is limited as viral infections can also give rise to high CRP levels." (PMID 38184547, 2024). "During viral infections, CRP levels can rise significantly, often reaching 10–60 mg/L." (PMID 39589620, 2024). "Similarly, CRP values were significantly higher in the viral infection and bacterial infection groups, with a slight increase from the first to third days of life." (PMID 38790588, 2024). "In such cases, by promptly confirming a viral infection with quantitative MxA measurement, possibly in combination with low CRP or procalcitonin level, it might be possible to reduce both additional diagnostic testing and unnecessary use of antibiotics." (PMID 39041941, 2024). "Elevated CRP levels indicate systemic inflammation, which is common in viral infections." (PMID 39589620, 2024). "CRP stands as one of the most widely utilized inflammatory markers, typically exhibiting minimal or no increase during viral infections except in cases of severe viral infections that induce tissue and organ damage." (PMID 38915920, 2024). "Indeed, the MxA/CRP ratio differed significantly between viral infections and co-infections and allowed a more reliable differentiation between viral and bacterial infections in our study." (PMID 36737561, 2023). "These were classified as having probable bacterial infection (n = 17), probable viral infection (n = 13) and fever of unknown origin (n = 13) based on microbiological defined infections and CRP cut-off levels." (PMID 37371198, 2023). "Indeed, it is commonly accepted that viral infections give rise to moderate increases in CRP values, usually up to 25 mg/L." (PMID 37763974, 2023). "Furthermore, CRP is an important biomarker used in diagnostics to predict risk of cardiovascular disease (CVD) in addition to monitoring bacterial and viral infections." (PMID 36781868, 2023). "Regarding infectious diseases, CRP is elevated in bacterial, fungal, and viral infections However, even considering the limits exposed above, C-reactive protein retains a strong negative predictive value in ruling out the presence of an active bacterial infection, especially LRTI." (PMID 36673130, 2023). "For viral infections only slight elevations of CRP levels (<5 mg/L) have been reported." (PMID 35345614, 2022). "Importantly, CRP plasma levels in viral infection are usually significantly lower than CRP levels in bacterial infection." (PMID 35407379, 2022). "C-reactive protein (CRP) is a sensitive biomarker of viral infection and inflammation." (PMID 35677912, 2022). "First, there was only one measure of CRP, which could have led to misclassification of some participants with a self-limited condition such as a viral infection." (PMID 36030344, 2022). "CRP remains at a level of 10–40 mg/L, indicating virus infection or chronic inflammation." (PMID 36553115, 2022). "In a recent head-to-head comparison of another blood transcriptional signature and CRP to discriminate bacterial and viral infections, we found the transcriptional signature to be more useful in detection of viral infections, but CRP to be more useful in identifying bacterial infections." (PMID 36543100, 2022). "However, there is a substantial range of CRP values that correlate with bacterial as well as with viral infections, and therefore cannot be relied upon to differentiate between these two types of infectious etiologies." (PMID 35897672, 2022). "Biomarkers and point-of-care tests to rapidly differentiate bacterial from viral infections may be helpful, such as combined C-reactive protein and myxovirus resistance protein A immunoassay, or human neutrophil lipocalin assay." (PMID 36325426, 2022). "Negative correlation between eotaxin and CRP levels in our patients indicated that progressive eotaxin decline was linked with inflammation and worsening of viral infection." (PMID 36012146, 2022).
viral infections (continued). "Previous studies also showed that by developing a duplex test for simultaneous detection of both PCT and CRP antigens, we could increase the sensitivity and specificity for differentiating bacterial and viral infections at the point-of-care." (PMID 35149284, 2022). "Nevertheless, CRP was better than PCT at discriminating viral infections from bacterial infections." (PMID 36141662, 2022). "The most important finding of the present study was that a concentration of CRP ≤ 22 mg/L or PCT ≤ 0.18 ng/mL combined with rhinorrhea could help to discriminate a bacterial infection from a viral infection." (PMID 34583675, 2021). "CRP has been reported as an indicator of bacterial coinfection in viral pneumonia patients with a cut off value of more than 40 mg/L for mixed coinfection and lower for sole viral infection." (PMID 33816347, 2021). "However, CRP also has its drawbacks as some studies have reported CRP levels to remain stable or to be only moderately elevated upon particular viral infections; hence, the optimal marker for inflammation remains yet to be established." (PMID 34071813, 2021). "However, we note that other potential indicators for severe viral infection, like increased temperature and markers of immune system activation, e.g. C-reactive protein, are less prominent in our feature importance scores." (PMID 33603086, 2021). "Specific markers of viral infection such as CXCL10/IP-10 or macrophage activation such as sCD14 may also be more sensitive to HCMV reactivation than CRP." (PMID 33500556, 2021). "Moreover, autoimmune diseases are generally known to initiate, exacerbate or relapse upon bacterial or viral infections which inflict CRP upregulation." (PMID 33790888, 2021). "PCT also has a significantly higher accuracy than CRP for discriminating between bacterial and viral infections or non-infective causes of inflammation." (PMID 34066811, 2021). "Nevertheless, for the assessment of host inflammatory status and identification of viral infection in other pathologies, such as bacterial sepsis, the acute-phase proteins, including CRP and procalcitonin, can provide more important information for guiding clinical diagnosis and antibiotic therapy." (PMID 34447386, 2021). "In addition, also in some viral infections CRP and PCT can be increased, as observed in enteroviral or respiratory syncytial virus infections, as well as in severe SARS-CoV-2 infections with concomitant inflammation." (PMID 34079538, 2021). "CRP is widely used in clinical practice in the evaluation of disease severity during different infections as well as inflammatory disorders, and it is also used to discriminate between bacterial and viral infections, although the concentrations partly overlap." (PMID 35062248, 2021). "In general, it is assumed that viral infection increases CRP levels by 10 to 40 mg/L29–31." (PMID 33436908, 2021). "Under circumstances where viral infection is less likely both CRP and PCT are good indicators for the need to treat with antibiotics, such as in febrile neonates and very young infants when disease is often caused by Streptococcus agalactiae or Escherichia coli infection postpartum." (PMID 34079538, 2021). "Samples of viral infections recorded the lowest CRP values (8 mg/L, IQR 3–23, n = 126)." (PMID 33647009, 2021). "The new three-gene signature provided the greatest overall net benefit to trigger an intervention for definite or probable viral infection, whereas CRP provided the greatest overall net benefit to trigger an intervention for definite or probable bacterial infection." (PMID 34423323, 2021). "C-reactive protein (CRP) and procalcitonin are biomarkers that have been suggested to distinguish bacterial from viral infections, but their usefulness lies in repeated measures in hospitalized patients, and have not been proven useful in diagnosing pharyngitis in adults." (PMID 33686635, 2021).
viral infections (continued). "However, WBC counts and CRP levels can also be elevated in various types of systemic inflammations and viral infections, thus limiting their ability to distinguish bacterial from viral etiologies of meningitis." (PMID 34066811, 2021). "Specific markers of a viral infection such as CXCL10/IP-10, macrophage activation such as sCD14, or HCMV encoded microRNAs may be better markers of HCMV activity than IgG level or CRP concentration, however, more research is needed to answer this question." (PMID 34493708, 2021). "Increased levels of CRP were also found in severe virus infections." (PMID 34926619, 2021). "By applying a cut-off of <10 mg/L, CRP may serve as a rough discriminator of bacterial from viral infections, since bacterial infections typically yield higher levels of circulating CRP." (PMID 34408755, 2021). "In our research, the elevation of CRP was correlated with the risk of infections, and 12 (57.1%) patients with viral infection were accompanied by elevated CRP, while the rate of increased CRP was 38.6% in patients without viral infection." (PMID 32972385, 2020). "CRP is an acute phase protein synthesized by the liver in response to IL-6 increase, which is used as a biomarker of inflammation and to distinguish between bacterial and viral infections." (PMID 32256905, 2020). "We then sought to benchmark the application of SeptiCyteTM TRIAGE, by itself and in combination with SeptiCyteTM VIRUS, against the performance of peripheral blood leukocytes and CRP to discriminate between confirmed bacterial and viral infections in unselected adults presenting to ED with fever." (PMID 32690014, 2020). "In the subsequent stage of viral infection, the leukocyte or neutrophil count may increase after combined bacterial infection, and the CRP level and procalcitonin content can similarly further rise." (PMID 32574297, 2020). "However, whereas bacterial infections generally result in impressive CRP levels, the response in many viral infections is typically less pronounced." (PMID 33584722, 2020). "In addition, CRP values in other viral diseases, such as H1N1 influenza, were higher for patients with a serious history of the disease." (PMID 32894449, 2020). "CRP is a valuable marker for distinguishing bacterial infections from viral infections." (PMID 31428091, 2019). "Similarly, CRP is a low-specific marker because it increases at 12 to 18 hours after tissue damage due to bacterial or viral infections." (PMID 31358829, 2019). "In this study, we investigated the causes of fever in hospitalised patients in Chiangrai, northern Thailand, and assessed if two chemical markers (CRP and procalcitonin) could distinguish bacterial from viral infections." (PMID 29852003, 2018). "Biomarkers such as C-reactive protein (CRP) and procalcitonin have some utility in delineating between bacterial and viral infections and guiding healthcare workers on the appropriate use of antibiotics in patients with respiratory tract infections in high income settings." (PMID 29852003, 2018). "Procalcitonin has been found to have better specificity, sensitivity, predictive value and likelihood ratio than CRP, interleukin 6 and interferon-alpha in children for distinguishing between bacterial and viral infections in other studies from various parts of the world." (PMID 30388962, 2018). "We observed that the host-protein signature yielded significantly superior performance for diagnosing bacterial versus viral infections in these patients as compared to the individual biomarkers CRP, PCT, WBC, ANC, IL-6, and HNL, and their currently used combinations." (PMID 29700762, 2018). "They found that the combination of CRP, IP-10, and TRAIL improved diagnostic ability to distinguish bacterial from viral infections and may help in rational use of antibiotics in children." (PMID 28915908, 2017).
viral infections (continued). "In this study, 38% of patients with microbiologically confirmed viral infection had an elevated CRP ≥ 20 mg/L and 17% had an elevated PCT ≥ 0.1 ng/ml which could contribute to overtreatment." (PMID 28991170, 2017). "CRP levels above this threshold identify a clinically significant immune response but cannot reliably differentiate between viral and bacterial etiology; therefore, FebriDx also includes MxA as a marker of viral infection." (PMID 28991170, 2017). "It is also seen in this report that the clinical performance of HNL seems no better than that of CRP in the diagnostic distinction between bacterial and viral infections." (PMID 28468981, 2017). "Nevertheless, the functional role of increased CRP in multiple bacterial and viral infections as well as in chronic inflammatory diseases remains unclear." (PMID 28922377, 2017). "However, when compared with CRP alone, the combined assay has been found to improve the identification of patients with viral infection (8.6%) but to be similarly effective in classifying bacterial cases." (PMID 28218726, 2017). "The combination of bacterially-induced and virally-induced biomarkers was a more robust method (p<0.001) for discriminating bacterial from viral infection than CRP, TRAIL, or IP-10 individually, as well as other routinely used clinical parameters and other combinations of biomarkers (p<0.001)." (PMID 27486746, 2016). "However, the serum CRP concentrations were significantly higher in children with probably bacterial CAP than in those with probable viral disease (32.2 ± 55.5 mg/L vs 9.4 ± 17.00 mg/L, p < 0.05)." (PMID 27439403, 2016). "However, the CRP serum concentrations were significantly higher in children with probable bacterial CAP than in those with probable viral disease (32.2 ± 55.5 mg/L vs 9.4 ± 17.0 mg/L, p < 0.05)." (PMID 27439403, 2016). "Viral infections elevate MxA levels while only having a modest increase in CRP levels." (PMID 26672961, 2015). "Using a combination of MxA and CRP as indicators of infection, the ROC curve, sensitivity, and specificity for differentiating between bacterial and viral infections was 0.84 (95% CI: 0.75–0.94), 80.9% (95% CI: 66.7–90.8), and 87.9% (95% CI: 71.8–96.5), respectively." (PMID 26672961, 2015). "Neutrophil activation markers such as calprotectin, alone or in combination with other inflammation markers, could potentially be superior to e.g. CRP to distinguish between bacterial and viral infections." (PMID 26213499, 2015). "Procalcitonin and CRP levels were significantly lower in patients with a viral infection than other infections (p < 0.0001 in all comparisons apart from procalcitonin values in the Cambodian site where this was p = 0.01 for the difference between viral and bacterial infections)." (PMID 26558692, 2015). "The safety profile was such that physiological responses to viral infection were detected (elevated C-reactive protein and elevated monocytes, pyrexia and upper respiratory tract symptoms), but were not of such severity to cause irreversible damage or be of clinical concern." (PMID 25645025, 2015). "In an immune-competent person, PCT and CRP are ideal biomarkers for determining a host response consistent with a bacterial confirmation while MxA serves to confirm the presence of a significant viral infection." (PMID 26672961, 2015). "Procalcitonin and CRP levels were compared amongst these aetiological groups and their sensitivity and specificity in distinguishing bacterial infections and bacteraemias from viral infections were estimated using standard thresholds." (PMID 26558692, 2015). "The second, which is specific to the targeting of CRP genes, is the potential impact that high frequency viral infections could have in increasing the fitness of {Ud} heterozygotes." (PMID 24844466, 2014). "We found that CRP was weakly positive in only 3 of 16 patients with viral infections." (PMID 24764729, 2014).